IL6 (interleukin 6)
Diseases named in the same sentence as IL6 in open-access papers (continued):
Sharing a sentence is not in itself a finding about the gene and the disease.
cardiomyopathy (76 papers, 2006 to 2026). A disease of the heart muscle or myocardium proper. "While IL-6 is usually recognized as pro-inflammatory cytokine that causes cardiomyopathies, our results reveal a previously unappreciated role of IL-6 as a novel cardiac protective/pro-regenerative factor." (PMID 35101092, 2022). "We also describe novel associations between specific IL18, IL17A, and IL1B variant profiles and the risk of cardiomyopathy as well as between a specific IL6 polymorphic genotype and the risk of positive T. cruzi parasitemia." (PMID 33193300, 2020). "One of the most important cytokines in cytokine release syndrome is IL-6 which aggravates the patients clinical condition by causing vascular leakage, complement activation and coagulation cascade imbalance along with cardiomyopathy damaging myocardial cells." (PMID 33425279, 2020). "IFN-γ, TNF-α and IL6 cytokines secretion levels were higher in patients at the asymptomatic phase of the disease than in Chagas patients with associated cardiomyopathy." (PMID 25816096, 2015). "The same concentration in spontaneously hypertensive (SH) rats caused cardiomyopathy, monocytic cell infiltration, and increased expression of cardiac cytokines interleukin-6 and transforming growth factor-β." (PMID 17107850, 2006). "It is already known that patients with sepsis-associated cardiomyopathy have an exacerbated inflammatory status that is characterized by elevated circulating levels of several cytokines, including the previously-mentioned IL-6 and TNF-α." (PMID 35888173, 2022). "High levels of inflammatory markers, especially IL-6, might be a clue to finding a possible common pathophysiology for pregnancy-associated cardiomyopathy and COVID-19 related cardiomyopathy." (PMID 33741059, 2021). "Studying the role of inflammatory cytokines such as IL-6 in the process of myocardial injury might shed light on the pathophysiology underlying pregnancy and COVID-19-related cardiomyopathy." (PMID 33741059, 2021). "Novel therapeutics directly targeting key inflammatory pathways, such as IL-6 inhibitors and colchicine, are also of interest, but are yet to be investigated in cardiomyopathy." (PMID 40149601, 2025). "Molecular evidence of cardiomyopathy, including inflammation marker (Tnd and Il6), fibrosis marker (Col1a1 and Col3a1), and hypertrophy marker (Nppa, Nppb, and Myh7), significantly increases when Rab7 was knocked out." (PMID 38837607, 2024). "Acute myocardial injury in the context of CRS shares similarities with sepsis-related cardiomyopathy and is thought likely to be mediated by interleukin-6, a cytokine elevated during infectious and inflammatory processes." (PMID 39211749, 2024). "LLLT can suppress circulating cytokines levels, in particular, tumor necrosis factor-α (TNF-α) and interleukin (IL)-6, these cytokines can promote progressive left ventricular (LV) dysfunction, LV remodeling, and cardiomyopathy." (PMID 36780088, 2023). "Endothelin signaling was activated in LMNA mutant cardiomyopathy, whereas IL6 signaling was activated in TTN mutant cardiomyopathy." (PMID 36950287, 2023). "It is important to note that IL-6 is related to induce cardiomyopathies by the stimulation of coronary artery disease and myocardial dysfunction." (PMID 33946736, 2021). "Herein we investigated potential associations between IL1B, IL6, IL17A, or IL18 polymorphism profiles and cardiomyopathy or T. cruzi parasitemia, as well as the impact of HIV infection on cardiopathy." (PMID 33193300, 2020). "Previous studies showed direct correlation between IL-6 serum levels and cardiomyopathy and an inverse correlation between IL-6 levels and LVEF in the setting of cardiopathy." (PMID 33193300, 2020). "Patients with severe cardiomyopathy exhibited increased IL-6 levels compared with patients with less severe forms of the disease and uninfected subjects." (PMID 30517089, 2018).
cardiomyopathy (continued). "The molecular mechanism of IL-6 in cardiac FA metabolism is not fully understood yet, but it is important to address it due to the important roles in development of various cardiomyopathy." (PMID 30134607, 2018). "Dox-induced cardiomyopathy is also associated with increased levels of the MMP2- and 9, and pro-inflmammatory cytokines TNF-α, IL-1β, and IL-6 as similar to the results observed in kidney." (PMID 25742619, 2015). "However, IL-6 seems to represent a pivotal mediator in cytokine release syndrome-related cardiomyopathy, consistent with observations in sepsis-related cardiomyopathy." (PMID 41374942, 2025). "Additionally, MSE also downregulated the expression of inflammatory markers such as TNF-α and IL-6 which were known to be critical in cardiomyopathy." (PMID 33747350, 2021). "Investigation of the involvement of miRNAs in the regulation of heart aging through inflammatory responses showed that the miRNA let-7 inhibits angiotensin II-induced cardiomyopathy and fibrosis by inhibiting the expression of IL-6 and multiple collagens in the heart." (PMID 33593281, 2021). "This inflammatory cascade activates T cells and immune effector cells, including macrophages and endothelial cells, to produce inflammatory mediators, such as tumor necrosis factor and interleukin-6 (IL-6), associated with disseminated intravascular coagulation (DIC) and cardiomyopathy." (PMID 33467705, 2021). "For example, over-expression of TNF-α, IL-1 and IL-6 in the immune system could lead to vascular leakage, systemic fatigue, cardiomyopathy and acute-phase protein synthesis." (PMID 34457338, 2021). "The IL-6 immune protein solely can lead to cardiomyopathy during serious CRS conditions." (PMID 33946736, 2021). "Facing the biological and clinical scenarios just described, in the current study we investigated potential associations between SNVs linked to IL1B, IL6, IL17A, or IL18 and the risks of positive T. cruzi parasitemia or development/progression of cardiomyopathy." (PMID 33193300, 2020). "The inhibition of IL-6/STAT3 signaling pathway may offer a new target for cardiomyopathy." (PMID 35402550, 2022). "For instance, overexpressed TNF-α, IL-1, and IL-6 could induce fever, general malaise, fatigue, vascular leakage, diarrhea, cardiomyopathy, lung injury, vascular leakage, acute-phase protein synthesis, complement system activation, and diffuse intravascular coagulation." (PMID 33553280, 2020). "To demonstrate the anti-inflammatory effects of AKBA, we assessed the production levels of proinflammatory cytokines, including TNF-α, IL-6, IL-1β, and PGE2, which contributed to LPS-induced cardiomyopathy." (PMID 35399644, 2022). "Lnc‐MEG3 expression was positively correlated with cardiomyopathy, APACHE II score, SOFA score, Scr, TNF‐α, IL‐1β, IL‐6, and IL‐17, 28‐day deaths, while negatively correlated with albumin." (PMID 34956235, 2021). "Elevated levels of TNF-α and IL-6 have indeed been reported in BTHS patients, further exacerbating their cardiomyopathy." (PMID 33001359, 2021). "Exercise training has been shown to elevate AKT phosphorylation in the dilated heart with cardiomyopathy and to attenuate the isoprenaline-stimulated NF-κB, TNF-α, IL-6, and TGF-β1 in the myocardium." (PMID 32354131, 2020). "HIV-mediated cytokine dysregulation may lead to an increase in tumor necrosis factor-alpha (TNF-alpha), interleukin-1 (IL-1), and IL-6, and thus be an important contributor to the development of HIV cardiomyopathy." (PMID 36127962, 2022). "On the other hand, although circulating TNF-α and IL-6 levels are known to increase in human cardiomyopathy, this study did not detect an increase in SAA concentration in cardiomyopathy." (PMID 32326517, 2020). "We conclude that NS-cardiomyopathy involves cardiomyocytes, ECs and fibroblasts, TNF/IL6 signalling components represent potential therapeutic targets, and abnormal EC signalling might contribute to other forms of LVH." (PMID 28548091, 2017).
cardiomyopathy (continued). "In subjects with cardiomyopathy who were treated with ivabradine, inflammatory biomarkers, namely tumor necrosis factor α (TNFα), growth-differentiation factor 15 (GDF-15), heart-type fatty acid binding protein (H-FABP), and interleukin 6 (IL-6), were attenuated." (PMID 36769115, 2023). "Given that BTHS is characterized by cardiomyopathies, it would not be surprising to observe increased levels of TNF-α and IL-6 in this disease state." (PMID 33001359, 2021). "Given that BTHS is characterized by cardiomyopathies, it would not be surprising to expect increased levels of TNF-α and IL-6 in this disease state." (PMID 33001359, 2021). "Analysis of serum samples further showed elevated soluble MD2, inflammatory cytokines TNF-α and IL-6, and MD2-AGE complexes in diabetic subjects with DCM and without cardiomyopathy, compared with healthy samples." (PMID 32358497, 2020). "Systemic cytokine levels were low (IL-6 and IL-10) or undetectable (TNF-α) with or without induction of takotsubo-like cardiomyopathy." (PMID 30623136, 2018). "In our study, however, no significant changes were found in either the serum or cardiac levels for IL-6 and cardiac TNF-α, suggesting that inflammation is not the key factor of the early changes related to cardiomyopathy." (PMID 23497124, 2013).
hypercoagulability (76 papers, 2009 to 2025). "Perpetually elevated IL-6 levels are associated with hypercoagulability, and both IL-6 and CRP levels have been used as markers for cardiovascular disease." (PMID 35814772, 2022). "In vitro experimental studies demonstrate that interleukins (IL), such as IL-6, IL-1 are able to cause hypercoagulability through stimulation of tissue factor activity." (PMID 19254383, 2009). "For example, COL2A1 mutations weaken the strength of the epiphyseal cartilage matrix, mutations in Factor V Leiden, and deficiencies in Protein-C and Protein-S contribute to thrombophilia, while nitric oxide synthase and IL-6 gene polymorphisms potentially affect endothelial cell function." (PMID 40041162, 2025). "In order to quantify the extent of the inflammatory process, we determined the levels of proinflammatory cytokines—TNF-α and IL-6 in the blood plasma of the studied groups of women as well as the carriage of 675 4G/4G polymorphism in the PAI-1 thrombophilia gene." (PMID 35955896, 2022). "It was postulated that IL-6 and IL-8 may cause a hypercoagulable state, leading to scattered fibrin clots, shortening the clot dissolution time, and maximizing the dissolution rate." (PMID 34680795, 2021). "In addition, HSA was associated with markers of systemic inflammation and hypercoagulation (interleukin 6, tumour necrosis factor α, C-reactive protein, fibrinogen and D-dimer)." (PMID 34948066, 2021). "Furthermore, it has been shown that HSA is associated with markers of systemic inflammation and hypercoagulation (interleukin 6, tumor necrosis factor α, С-reactive protein, fibrinogen, and D-dimer)." (PMID 31703357, 2019). "A progressive dysregulated coagulative response to SARS‐CoV‐2 viral infection with the synthesis of IL‐6 and other inflammatory mediators (the so‐called cytokine storm) contribute in turn to activate the complement system, clotting cascade, thus causing a state of hypercoagulability." (PMID 33176009, 2020). "In conclusion, our results may suggest that both SH and OH may be associated with ED, which is reflected by decreased fibrinolytic activity, hypercoagulability, and increased levels of IL-6, IL-12, and IL-18 and depends not only on the cause but mainly on the degree of hyperthyroidism." (PMID 24367378, 2013). "Severe long cases showed an overreaction of the immune system with IL‐6 cytokine storm and hypercoagulability." (PMID 40183283, 2025). "Elevated fibrinogen, factor VIII, and von Willebrand factor levels promote a hypercoagulable state, while cytokines like IL-6 and TNF-α drive persistent inflammation." (PMID 41181439, 2025). "In patients with COPD, hypercoagulability is primarily driven by chronic hypoxia and inflammatory factors (including IL-6 and TNF-α)." (PMID 40421211, 2025). "In particular, the thrombophilia group had interleukin-6 (IL-6) levels that were significantly higher (14.8 pg/mL, SD: 3.2) than the control group (12.4 pg/mL, SD: 2.1), with a p-value of 0.029." (PMID 38533322, 2024). "Another plausible explanation of the hypercoagulability in patients with COVID‐19 is the presence of high levels of interleukin‐6 (IL‐6) and supported by the potential benefit of IL‐6 inhibitors like tocilizumab in severe COVID‐19 patients." (PMID 36572657, 2023). "Some proinflammatory cytokines, such as TNF-α, IL-1 and IL-6, can promote the expression of procoagulant molecules and inhibit the expression of anticoagulant molecules, eventually leading to hypercoagulability." (PMID 34319903, 2021). "Increased circulating levels of coagulation factors and platelets have been reported in cachectic C26 tumour‐bearing mice, and hypercoagulability in this model is partially IL‐6 dependent." (PMID 34427055, 2021). "In C26 mouse model of cancer cachexia, hypercoagulation was observed due to partially elevated inflammatory cytokine levels, including IL-6." (PMID 33334063, 2020).
hypercoagulability (continued). "Moreover, high-DII diets increase the production of pro-inflammatory cytokines, such as interleukin-6 and tumor necrosis factor-alpha, which trigger vascular inflammation and promote hypercoagulability." (PMID 40686813, 2025). "On the other hand, the excessive release of IL-6 in response to FgDP-monocyte interactions may exacerbate hypercoagulability, indicating a role for targeted inhibition of the FgDP–IL-6 axis." (PMID 41157266, 2025). "The actors of this cytotoxic effect could be local peritoneal cytokines: previous studies demonstrated that IL-1β and IL-6 induce structural and morphological changes in RBCs, eryptosis, and hypercoagulability." (PMID 38673869, 2024). "In addition, the alterations of the EPL thermograms correlate with the prevalence of the polymorphism in PAI-1 genes of thrombophilia and the increased levels of TNF-α and IL-6 established in the blood." (PMID 35955896, 2022). "We observe in our data that lower levels of thiols are related to an increase in hypercoagulability, D-dimer, and IL-6, all of which contribute directly to greater inflammation, an alteration in coagulation, and stress, coinciding with a worse clinical evolution." (PMID 34439469, 2021). "Inflammatory markers (CRP, IL-6) and d-dimer were elevated, indicating a hypercoagulable state." (PMID 32501751, 2020). "In particular, IL‐6 blockers like tocilizumab and sarilium could prevent the “cytokine storm” in severe forms of COVID‐19, and secondarily inhibit hypercoagulability." (PMID 33176009, 2020). "Levels of IL-6, sCD14 and sCD163 (both released by monocytes/macrophages), non-specific markers of inflammation (such as C-reactive protein and cystatin C), and markers of hypercoagulation and microbial translocation are variably increased during HIV-1 infection." (PMID 36672667, 2023). "Numerous studies have noted the superior safety profile of transdermal estrogen compared with oral, likely due to upregulation of proinflammatory cytokines IL-1, IL-6, IL-8, and TNF-alpha, which lead to increased thrombophilia when taken orally." (PMID 39659823, 2025). "Interleukin-6 (IL-6) and tumor necrosis factor-alpha (TNF-α) levels were higher in the study's thrombophilia group compared to the control group (p=0.029 and p=0.012, respectively), which is another important finding." (PMID 38533322, 2024). "Second, the increased IL-6 and TNF-α levels in the thrombophilia group point to a potential role for immunomodulatory interventions in treating these patients' repeated pregnancy losses." (PMID 38533322, 2024). "In a pathophysiological perspective, severe SARS-CoV-2 infection is characterized by numerous dependent pathways triggered by hypercytokinemia, especially IL-6 and TNF-alpha, leading to systemic inflammation, hypercoagulability, and multiple organ dysfunction." (PMID 34057983, 2021).
neutropenia (75 papers, 2008 to 2025). A decrease in the number of neutrophils found in the blood. "Regarding possible side effects, our results showed that IL-6 (receptor) antagonists were associated with an increased risk of neutropenia and an increased risk of impaired liver function based on moderate to high certainty evidence." (PMID 34728658, 2021). "AEs, likely caused as a direct consequence of an anti-IL-6 treatment, include rectal hemorrhage, thrombocyto- and neutropenia, abnormal liver function and infections." (PMID 32365499, 2020). "The conflict may be explained by the possibility that not all patients had achieved complete remission by Day 28, and were still experiencing neutropenia associated with fever and, consequently, elevated IL-6 levels." (PMID 40671161, 2025). "Interestingly, while dichotomized IL-6 retains a modest association with mortality, neutropenia, though useful for subdividing the hyperinflammatory phenotype, did not meaningfully affect outcomes (p = 0.5)." (PMID 41155261, 2025). "For the case of TNFi, the causes of neutropenia are different and varied: decreased upregulation of pro inflammatory cytokines (IL-1, IL-6, IL8 and granulocyte-macrophage colony-stimulating factor), all of them involved in the differentiation and maturation of neutrophils and hematopoietic cells." (PMID 39768600, 2024). "Because of the role of IL-6 in accelerating neutrophils’ release from the bone marrow into circulation, anti-IL-6 drugs may provoke an increase in transit time, causing transient neutropenia." (PMID 35645219, 2022). "However, based on in vitro evidence it is thought that IL-6 induces the release of neutrophils from marginated pools in the bone marrow; thus, inhibition of the IL-6 cascade might reverse this mechanism and cause neutropenia." (PMID 36091800, 2022). "Neutropenia associated with sJIA is dependent on IL-6 levels, and leukocytopenia and granulocytopenia may be used as biomarkers of susceptibility to treatment with IL-6 monoclonal antibodies." (PMID 34820342, 2021). "IL-6 was significantly higher in infections (median 80.81 vs. 13.37 pg/mL; p = 0.002), while G-CSF showed 14.6-fold elevation in Febrile Neutropenia with Detected Etiological Agent (FN-DEA) (p < 0.001)." (PMID 40647525, 2025). "A total of 82 of 99 neutropenia episodes were related to DMARDs, 60% to Anti-IL6 drugs in monotherapy, 13% to RA activity, 3% to infectious diseases and 1% to hematologic malignancy." (PMID 39768600, 2024). "No serious adverse events were reported in the REMAP-CAP study, and the CORIMUNO19 group reported a few cases of temporary neutropenia, which is a common side effect of all IL-6 blockers." (PMID 35645219, 2022). "After a week in the hospital, she developed MODS and extreme hyperferritinemia (21,378 ng/mL) and an elevated IL-6 (1,040.8 pg/mL); she also developed persistent pancytopenia (with both lymphocytopenia and neutropenia)." (PMID 35360192, 2022). "For example, elevated IL-6 concentrations are responsible for fever, hypotension, and neutropenia observed after CAR-T cell administration." (PMID 33921604, 2021). "There are few studies that analyzed together the kinetics of CRP, PCT and IL-6 in pediatric patients with fever and neutropenia and to our knowledge this is the first study that describes MR-proADM kinetics with the rest of them." (PMID 34828740, 2021). "Because most cases of neutropenia in this cohort were chemotherapy-induced, the relevant source of IL-6 could be neutrophils themselves or other immune cells also affected by chemotherapy." (PMID 41155261, 2025). "Our data indicate that septic patients with neutropenia, who display exceptionally high IL-6 levels and poor outcomes, may derive the greatest benefit from such targeted therapy." (PMID 41155261, 2025). "The study emphasized IL-6’s potential for low-risk stratification but cautioned against withholding antibiotics in neutropenia without validation." (PMID 40647525, 2025).